TLK1 (tousled like kinase 1)
Description:
Rapidly and transiently inhibited by phosphorylation following the generation of DNA double-stranded breaks during S-phase. This is cell cycle checkpoint and ATM-pathway dependent and appears to regulate processes involved in chromatin assembly. Isoform 3 phosphorylates and enhances the stability of the t-SNARE SNAP23, augmenting its assembly with syntaxin. Isoform 3 protects the cells from the ionizing radiation by facilitating the repair of DSBs. In vitro, phosphorylates histone H3 at 'Ser-10'.
Synonyms: KIAA0137; PKU-BETA
Tractability: Small molecule: a high-quality ligand is known; it belongs to a druggable protein family. PROTAC: ubiquitination databases record sites on it; a small molecule that binds it is known.
Target class: Other protein kinase TLK family; Protein Kinase; Kinase; Enzyme; Other protein kinase group
Gene: Protein-coding gene on chromosome 2 (170,990,823 to 171,231,314, reverse strand). Ensembl gene ENSG00000198586.
Subcellular location: Nucleus
Subcellular location (Human Protein Atlas): Nucleoplasm
Gene Ontology:
Molecular function: ATP binding; protein binding; protein serine kinase activity; protein serine/threonine kinase activity; protein kinase activity
Biological process: SNARE complex assembly; chromosome segregation; intracellular signal transduction; regulation of chromatin organization
Cellular component: nucleoplasm; nucleus
Genetic constraint (gnomAD): Loss-of-function variants: 17 observed, 75.55 expected, observed/expected ratio (o/e) 0.23, 90% interval 0.15 to 0.34. The upper end of that interval is the gene's LOEUF score, 0.34, which puts it in group 1 of 6, group 1 being the genes least tolerant of losing a copy. Missense variants: 447 observed, 756.1 expected, observed/expected ratio (o/e) 0.59, 90% interval 0.55 to 0.64. Synonymous variants: 272 observed, 263.74 expected, observed/expected ratio (o/e) 1.03, 90% interval 0.93 to 1.14.
Homologues: Orthologues: chimpanzee TLK1 (100% identical), macaque TLK1 (99% identical), pig TLK1 (99% identical), rabbit TLK1 (99% identical), dog TLK1 (99% identical), rat Tlk1 (99% identical), mouse Tlk1 (98% identical), guinea pig TLK1 (89% identical), tropical clawed frog pcmtd1 (88% identical), zebrafish tlk1b (83% identical), zebrafish tlk1a (81% identical), Drosophila melanogaster Tlk (51% identical), and 1 more. Paralogues in human: TLK2 (72% identical), TTK (20% identical).
Diseases named in the same sentence as TLK1 in open-access papers:
TLK1 is named in the same sentence as 30 diseases in open-access papers, as found by Europe PMC text mining. Sharing a sentence is not in itself a finding about the gene and the disease. The quoted sentences say what the papers report.
prostate carcinoma (6 papers, 2020 to 2024). A carcinoma that arises from epithelial cells of the prostate gland. "TLK1 has been linked to poor patient outcomes in multiple cancer types, including GBM39 and prostate cancer metastasis, and it is involved in DNA replication and chromatin assembly." (PMID 37868033, 2023). "Through in vitro kinase assays and docking studies, we report the synthesis and biological evaluation of a phenothiazine analog J54 with potent TLK1 inhibitory activity for prostate cancer (PCa) therapy." (PMID 32905878, 2020). "In different disease models such as prostate cancer (PCa) and glioblastoma (GBM) models, TLK1 depletion has been shown to elicit DNA damage response, and, therefore TLK1 forms a druggable target." (PMID 37686173, 2023).
breast carcinoma (4 papers, 2016 to 2023). "We also observe marker differences controversial to published correlations such as TLK1, which was believed to be most amplified in Luminal B breast cancer." (PMID 36598637, 2023). "TLK1 repression resulted in delayed S-phase progression in luminal breast cancers, suggesting its important role in cell cycle regulation." (PMID 29311920, 2017). "Silencing of TLK1 or TLK2 appears to result in distinct cell cycle alterations and different effects on apoptosis in luminal breast cancer cells overexpressing TLK2." (PMID 27694828, 2016).
glioblastoma (4 papers, 2020 to 2023). The most malignant astrocytic tumor (WHO grade IV). "Previous literature has shown that the knockdown of TLK1 inhibited the survival of glioblastoma polymorphic cells." (PMID 36947060, 2023). "It has been recently reported that the TLK1 paralog, TLK2, could form a complex with Src and activate the EGFR/Src/FAK signaling pathway to promote the migration and invasion of breast adenocarcinoma and glioblastoma cells." (PMID 36497211, 2022). "These include PCa stages according to Gleason score, head and neck squamous cell carcinoma, and glioblastoma, suggesting that this co-regulation is imparted by increased YAP1 stability when NEK1 is overexpressed or activated by TLK1, and not through transcriptional co-expression." (PMID 33297404, 2020).
cholangiocarcinoma (2 papers, 2023). A carcinoma that arises from the intrahepatic biliary tree (intrahepatic cholangiocarcinoma) or from the junction, or adjacent to the junction, of the right and left hepatic ducts (hilar cholangiocarcinoma). "First, these authors showed that TLK1 is abundantly expressed in cholangiocarcinoma as well as in cell lines derived from cholangiocarcinoma." (PMID 37686173, 2023). "TLK1 was overexpressed in both cholangiocarcinoma and cholangiocarcinoma cells and silencing of TLK1 enhanced cisplatin-stimulated DNA damage." (PMID 36947060, 2023). "Second, although siRNA knockdown of TLK1 did not affect the viability of cholangiocarcinoma cells, it sensitized these to cisplatin-induced apoptosis." (PMID 37686173, 2023).
ischemic stroke (2 papers, 2020). A stroke disorder caused by obstruction of blood flow to the brain, due to thrombotic (local blood clot formation) or embolic (due to a blood clot or other material traveling from another site) event. "Remarkably, circRNA TLK1 was observed to be also elevated in human patients after ischemic stroke." (PMID 32175077, 2020).
Sepsis (2 papers, 2022). Sepsis is defined as life-threatening organ dysfunction caused by a dysregulated host response to infection. "circR TLK1 contributes to sepsis-associated AKI by regulating inflammation and oxidative stress through the miR-106a-5p/HMGB1 axis." (PMID 35720285, 2022).
acute kidney injury (1 paper, 2023). Sudden and sustained deterioration of the kidney function characterized by decreased glomerular filtration rate, increased serum creatinine or oliguria. "Previous studies reported that circRNA TLK1 exacerbated myocardial ischemia–reperfusion injury and acute kidney injury by regulating inflammatory and oxidative stress, and promoted cancer progression." (PMID 37186176, 2023).
glioma (1 paper, 2023). A benign or malignant brain and spinal cord tumor that arises from glial cells (astrocytes, oligodendrocytes, ependymal cells). "It was shown that TLK1 expression was elevated in glioma tissues, and had correlation with large tumour volume and higher grade of glioma." (PMID 36947060, 2023). "Overexpression of TLK1 can significantly promote the growth, migration, and invasion of glioma cells, and inhibit cell apoptosis." (PMID 36947060, 2023).
hepatocellular carcinoma (1 paper, 2022). A malignant tumor that arises from hepatocytes. "Mounting evidence has shown that circular RNAs (circRNAs) function as key regulators in carcinogenesis and cancer progression, and this study is aimed at investigating the regulatory functions of circRNA TLK1 (circ-TLK1) in hepatocellular carcinoma (HCC)." (PMID 35359342, 2022).
Intellectual disability (1 paper, 2021). "Interestingly, SNPs in TLK1 have been associated with mathematical ability in GWAS studies, whereas pathogenic mutations in TLK2, a paralog of TLK1, have been reported in patients with ASD, intellectual disability (ID), schizophrenia, and microcephaly." (PMID 34069769, 2021).
Parkinson disease (1 paper, 2023). A progressive degenerative disorder of the central nervous system characterized by loss of dopamine producing neurons in the substantia nigra and the presence of Lewy bodies in the substantia nigra and locus coeruleus. "We have expanded on the proposed 17q21.31 linkage between SARS-CoV-2 and Parkinson’s disease by identifying 4 variants and 2 pleiotropic genes (i.e. TLK1 and FDFT1) in blood, located outside 17q21.31 and 6p21, that are also associated with both traits." (PMID 37336921, 2023).
prostate tumours (1 paper, 2022). "Our bioinformatic study also suggested a correlation of TLK1 and MK5 expression with the aggressiveness of prostate tumours, which hints towards a clinical relevance of TLK1‐MK5 signalling in PCa metastasis." (PMID 35064619, 2022).
renal cell carcinoma (1 paper, 2022). "circ-TLK1 (circbase ID: hsa_circ_0004442), derived from backsplicing the TLK1 mRNA, plays an oncogenic role in renal cell carcinoma." (PMID 35359342, 2022). "In renal cell carcinoma, circ-TLK1 exerts its oncogenic functions by sponging miR-136-5p." (PMID 35359342, 2022).
Stroke (1 paper, 2020). Sudden impairment of blood flow to a part of the brain due to occlusion or rupture of an artery to the brain. "It was increased in the mouse brain after tMCAO and knocking down circRNA TLK1 improve neurological deficits and infarct volume in this stroke mouse model." (PMID 32175077, 2020).
triple-negative breast carcinoma (1 paper, 2025). An invasive breast carcinoma which is negative for expression of estrogen receptor (ER), progesterone receptor (PR), and human epidermal growth factor receptor 2 (HER2). "MDA-MB-436, a triple negative breast cancer (TNBC) cell line with a natural BRCA1 mutation and the highest expression of TLK1 among the CCLE cell lines, exhibited significantly higher sensitivity to olaparib than MDA-MB-468, a BRCA1-proficient TNBC cell line, in a cell survival assay." (PMID 39844055, 2025).
cancer (20 papers, 2013 to 2025). A tumor composed of atypical neoplastic, often pleomorphic cells that invade other tissues. "Notably, overexpression of TLK1 has been associated with poor prognosis in various cancers and increased genomic instability." (PMID 39727191, 2025). "In a broader analysis across multiple cancers, high expression of TLK1 or TLK2 was significantly associated with poor prognosis in most of cancer types with wild-type BRCA1 (or low TLK1 associated with good outcome), but this was not seen in tumors with BRCA1 deficiency." (PMID 39844055, 2025). "Several human cancers have been identified that feature mutations in the kinase domain of TLK1, and high TLK1 expression levels correlate with radioresistance thus raising the possibility that TLK1 is an oncogene and potential therapeutic target." (PMID 24376897, 2013). "TLK1 is known to be highly expressed in several tumors and acts as an oncogene, aiding in cancer development and progression." (PMID 40369698, 2025). "In summary, PTH derivatives demonstrate promise as cancer therapies targeting TLK1/2-mediated DDR pathways." (PMID 39796704, 2024). "Together, these findings substantiate the potential use of PTH derivatives as alternative treatments for cancer by pharmacologically targeting the TLK1/2-mediated DDR pathways." (PMID 37446279, 2023). "This implies that TLK1 can regulate telomeric recombination as well and possibly mediate chromosome fusion during aberrant cancer hyper-recombination." (PMID 37686173, 2023). "Downregulation of miR-16 expression was observed in OSCC patients and cancer cell lines, and this was negatively correlated with enhanced expression of its target gene, Tousled-like kinase 1 (TLK1)." (PMID 35571032, 2022). "We propose that the TLK1>NEK1>YAP1 axis is a key determinant for cancer progression, particularly during the process of androgen-sensitive to -independent conversion during progression to mCRPC." (PMID 33297404, 2020). "This suggests that, in vivo, J54 may also modulate the proliferation of cancer cells, a property that we attributed earlier to the TLK1>NEK1>YAP1 axis that largely affects the contact inhibition features (mechano-transduction) of the cells." (PMID 40227796, 2025). "However, inhibiting TLK1 can transform these DSBs into a therapeutic vulnerability, leading to enhanced cancer cell death when paired with agents like CPT." (PMID 39796704, 2024). "Further investigations into TLK1 inhibition in combination with other DNA-damaging agents may pave the way for more effective and targeted treatments for PCa and other cancers that exhibit resistance to traditional chemotherapy agents." (PMID 38001987, 2023). "Note, however, that RWPE1 (a healthy prostate cell line with similar TLK1 expression) was insensitive to J54, suggesting that J54 may be a more targeted anti-cancer agent or the TLK1-NEK1 axis may remain critical even for the CRPC cells." (PMID 37446279, 2023). "This suggests that, in vivo, J54 may modulate also the proliferation of cancer cells, a property that we attributed earlier to the TLK1 > NEK1 > YAP1 axis, largely affects the contact-inhibition features (mechanotransduction) of the cells." (PMID 36497211, 2022). "Since TLK1 and TLK2 have higher sequence similarity and function similarly, we hypothesized that TLK1 may also play role in the dissemination of the cancer cells." (PMID 35064619, 2022). "Note, however, that RWPE1 (normal prostate) cell line was insensitive to J54, suggesting that J54 may be a more targeted anti-cancer agent, or it is possible that the TLK1>Nek1 axis remains critical even for CRPC cells." (PMID 32905878, 2020). "Moreover, TLK2 depletion culminates in a BLM-dependent, STING-mediated innate immune response, whereby, in many human cancers, TLK1/2 expression correlates with signatures of chromosomal instability and anti-correlates with STING and innate and adaptive immune response signatures." (PMID 37686173, 2023).
cancer (continued). "There are ongoing efforts to develop TLK1 and TLK2 inhibitors for targeting cancer cells with their promising roles in maintaining genome stability." (PMID 39727191, 2025). "Notably, TLK2 expression did not exhibit the same correlation with the DepMap score, suggesting that TLK1 and TLK2 may have differential effects on cellular sensitivity to PARP disruption in the context of BRCA1 deficiency, and that these effects may be cancer type- and context-dependent." (PMID 39844055, 2025). "A SNP on chromosome 2 (rs148374241) was mapped to tousled like kinase 1 (TLK1) gene, which is involved in cancer genesis." (PMID 41353206, 2025). "In conclusion, the genetic status and expression levels of TLK1 and TLK2 should be investigated as potential biomarkers for predicting resistance or sensitivity to PARPi therapy in cancers with HRD." (PMID 39844055, 2025). "An activating interaction between tousled-like kinase 1 (TLK1) and MK5 has been identified, increasing cell mobility and cancer metastasis." (PMID 40227796, 2025). "We propose that the signaling of TLK1>NEK1-mediated YAP phosphorylation and stabilization contributes not only to PCa progression, but also many other cancers." (PMID 33297404, 2020). "As expression of TLK1 and TLK2 exhibited significantly different patterns across cancer types, this emphasizes the need to consider the distinct genetic statuses and activities of TLK1 and TLK2 based on the cancer subtype for their application in therapeutic strategies." (PMID 39844055, 2025). "These insights establish TLKs as pharmacologically exploitable targets in ALT-driven tumors and chromosomally unstable cancers, while providing mechanistic context for understanding how the circ-MBOAT2 coordinates immune evasion in NSCLC pathogenesis through TLK1-dependent regulation." (PMID 40369698, 2025). "In addition, recent findings suggest that TLK1‐mediated activation of NEK1 also leads to apoptotic prevention and YAP stabilization, which facilitates cancer cell survival and conversion to androgen independence." (PMID 35064619, 2022). "We briefly elaborate on a non-canonical TLK1 isoform selectively expressed in eIF4E-rich cellular milieu and its role in limiting cancer treatment efficacy." (PMID 35048066, 2021). "Emerging evidence demonstrated that TLK1 and TLK2 are involved in cancer progression and therapeutic resistance and it has been shown that inhibition of TLK potentiates cell-killing in different types of cancers, making TLK1 and 2 attractive targets for therapeutic strategy development." (PMID 39727191, 2025). "In addition, as TLK1 plays important functions in the DDR and DNA repair, its inhibition in replication-stressed cancer cells could promote genomic instability and the generation of neoantigens, upon which a more effective immune response may ensue to curtail the rapid growth of tumors." (PMID 40227796, 2025).
tumor (8 papers, 2022 to 2025). "In contrast, these effects of upregulating miR-664b-3p on tumor cells were mitigated by overexpressing TLK1." (PMID 40369698, 2025). "A comparative analysis of circ-TLK1 expression profile in 87 specimens from HCC patients revealed significant upregulation of circ-TLK1 in HCC tissues compared to adjacent non-tumor tissues." (PMID 39596302, 2024). "Correlated increase of TLK1B and pNEK1 T141 with PCa progression was evident from a human PCa-TMA, TRAMP (a PCa mice model) and PDX tumor tissues; all suggested the universality of TLK1>NEK1 signaling in PCa models." (PMID 35582542, 2022). "Tumours with 1‐3 regional nodal metastatic lesions (N1) showed slightly higher expression of TLK1, but significant upregulation of MK5 compared to tumours with no nodal metastatic lesion (N0) was observed." (PMID 35064619, 2022). "Transwell assays demonstrated that TLK1 silencing impaired tumor cell migration and invasion." (PMID 40369698, 2025). "Moreover, high intra-tumor circ-TLK1 expression appeared to be closely correlated with a larger tumor size (p = 0.030), an advanced TNM stage (p = 0.018), and vascular invasion (p = 0.005)." (PMID 39596302, 2024). "miR-16 depletion promoted tumour advancement by activating TLK1 in oral squamous cell carcinoma." (PMID 36947060, 2023). "So in LGG, does ASF1B play a regulatory role in tumour by regulating TLK1?" (PMID 36947060, 2023). "We analysed the mRNA expression of both TLK1 and MK5 of PCa tumours with different nodal metastatic status using the UALCAN online bioinformatic tool." (PMID 35064619, 2022). "We interrogated publicly available databases to determine TLK1 and MK5 status in actual PCa patients with advanced tumours." (PMID 35064619, 2022). "Functional experiments further confirmed that circ-TLK1 knockdown inhibited, while circ-TLK1 overexpression promoted the malignant behaviors of HCC cells, suggesting that circ-TLK1 might act as an oncogene rather than a tumor suppressor in HCC." (PMID 35359342, 2022). "Similarly, consistent upregulation of both TLK1 and MK5 was observed in tumours with increasing Gleason scores, although our driving hypothesis is that it is the activity of MK5 (via upregulation by TLK1) that is really more significant." (PMID 35064619, 2022). "Similarly, NEK1 T141A overexpressing LNCaP and xenograft tumor remain sensitive to ADT and do not transition to AI growth, which confirms the persistence of TLK1>NEK1 signaling in PCa drug resistance to ADT." (PMID 35582542, 2022).
TLK1 also shares sentences with these, for which no sentence is quoted: adenocarcinoma (1 paper); brain ischemia (1); breast adenocarcinoma (1); head and neck squamous cell carcinoma (1); microcephaly (1); myocardial ischemia (1); neurodegenerative disease (1); neurological disorders (1); non-small cell lung carcinoma (1); ovarian carcinoma (1); prostate adenocarcinoma (1); schizophrenia (1); squamous cell carcinoma (1).